L1CAM (L1 cell adhesion molecule)
Diseases named in the same sentence as L1CAM in open-access papers (continued):
Sharing a sentence is not in itself a finding about the gene and the disease.
colorectal cancer (34 papers, 2010 to 2025). A primary or metastatic malignant neoplasm that affects the colon or rectum. "In colorectal cancer, L1CAM caused upregulation of clusterin expression in cancer cells as a result of the transactivating effect of STAT1 on clusterin." (PMID 35003395, 2021). "Colorectal cancer patients with high expression of L1CAM have higher risk of early metastasis." (PMID 35395711, 2022). "While its promise is evident, translating L1CAM into a diagnostic and prognostic biomarker requires further validation across diverse patient cohorts to ensure its broader applicability and efficacy in managing conditions raised from chronic colonic inflammation, such as colorectal cancer (CRC)." (PMID 37893107, 2023). "L1CAM has been extensively investigated in the last 15 years in relation to its capacity in enhancing cell motility and thereby promoting invasiveness and its expression has been reported be associated with many cancers including breast, gastric and colorectal cancers." (PMID 29980240, 2018). "Recent work has also suggested that L1CAM upregulation marks metastasis-initiating cells in colorectal cancer and defines a new cancer stem cell population in ovarian cancer." (PMID 41039222, 2025). "In this regard, the significant homology between CDH17 and L1CAM RGD motifs would suggest a simultaneous blocking of both activities by the RGD-specific monoclonal antibodies in colorectal cancer." (PMID 41039222, 2025). "The cell adhesion molecule L1CAM (L1), mainly known for its function in brain cells, is a Wnt/β-catenin signaling target gene in colorectal cancer (CRC) cells, where it promotes invasion and liver metastasis." (PMID 39513917, 2024). "For example, in colorectal cancer, cells expressing the L1 cell adhesion molecule (L1CAM) have chemoresistance and the ability to initiate metastasis." (PMID 37958607, 2023). "In the previous study focusing on colorectal cancer, two adhesion proteins (N-Cadherin and L1-CAM), known markers of the epithelial-to-mesenchymal transition, were investigated as potential future targets in cancer treatment." (PMID 35884357, 2022). "Recently, in colorectal carcinoma, Ganesh et al37 have established a link between L1CAM and cancer stemness, where L1CAM characterizes a CD133/CD44 expressing stem‐like cells population endowed with enhanced tumorigenic potential and increased chemoresistance." (PMID 35429348, 2022). "All samples from patients with colorectal cancer reproducibly demonstrated the presence of L1CAM, CXCR4 and ALK4 -positive cells in the invasive front with histological evidence for cell dissemination." (PMID 33897875, 2021). "For instance, upregulation of L1 cell adhesion molecule (L1CAM) initiates outgrowths of colorectal cancer into perivascular sites." (PMID 35009324, 2021). "The expression of L1CAM protein in cancer tissues and adjacent normal tissues of patients with breast and colorectal cancer was analyzed by immunohistochemical method." (PMID 32742486, 2020). "In colorectal cancer, cells expressing L1 cell adhesion molecule (L1CAM) confer metastasis-initiating abilities and chemoresistance." (PMID 32296047, 2020). "Aberrant L1CAM expression in colorectal cancer correlated with advanced stage and presence of lymph node and distant metastases." (PMID 24422715, 2013). "The authors analysed colorectal carcinoma cell lines and tumor tissues and found a good correlation between L1CAM immunoreactivity and methylation status." (PMID 23530769, 2013). "A recent study on L1CAM expression in colorectal cancer has shown that the L1CAM promoter regions (including promoter 1 and 2) are subject of comprehensive changes in DNA methylation of CpG islands." (PMID 20799950, 2010). "L1CAM defines the regenerative origin of metastasis-initiating cells in colorectal cancer." (PMID 36117173, 2022).
colorectal cancer (continued). "In recent years, L1CAM has been found to be highly expressed in many tumor cell lines and tumor tissues—for example, in glioblastoma, metastatic brain tumors, endometrioid adenocarcinoma, colorectal cancer, and lung cancer." (PMID 35003395, 2021). "For example, L1CAM has been recently proposed as a biomarker of CSC in colorectal cancer." (PMID 34645505, 2021). "The interaction of L1CAM with ezrin, and downstream activation of NF-κB is elevated in invasive colorectal tumor fronts and is necessary for proliferation, invasion and metastasis of colorectal cancer cells." (PMID 31455004, 2019). "Studies in colorectal cancer cell lines have shown that β-catenin (CTNNB1) mutations, and the subsequent aberrant activation of the Wnt signalling pathway, result in upregulation of L1CAM." (PMID 27028855, 2016). "For L1CAM, regulation of transcription by TGF-β signaling has been described, but, interestingly, in colorectal cancer L1CAM has also been shown to be a target gene of Wnt/β-catenin signaling and expression of L1CAM was found to co-localize with β-catenin in the invasive front of the tumor." (PMID 22295114, 2012). "Additionally, the proproliferative effects seen after L1CAM overexpression in our study could possibly be induced through the upregulation of ezrin, as in colorectal cancer, ezrin also mediates proliferation, motility, and metastatic capacity via L1CAM." (PMID 34228897, 2022). "Previous studies indicate that L1CAM, situated specifically at the invasive front of tumor tissues, serves as a target for activation by β-catenin-TCF signaling in colorectal cancer." (PMID 35473609, 2022). "Histological analyses on several primary tissues revealed that L1CAM, CXCR4 and ALK4 (the Nodal-receptor) have a similar expression pattern (insets) and were anatomically localized in the bulk tumor and in the invasive front of colorectal cancer samples." (PMID 33897875, 2021). "Based on our idea that Nodal signaling regulates the aggressiveness of the tumor cells through L1CAM and CXCR4, we investigated whether inhibition of Nodal signaling by SB431542 translates into increased progression-free survival in pre-established colorectal cancers." (PMID 33897875, 2021).
lung carcinoma (33 papers, 2017 to 2026). "In this study, we used Weighted Gene Co-Expression Network Analysis (WGCNA) to identify prognostic genes associated with L1CAM in lung cancer brain metastasis." (PMID 39697539, 2024). "Recent studies have indicated that L1CAM expression in tumors is associated with poor prognosis, also in lung cancer, and this protein seems to promote tumorigenicity and metastatic potential in NSCLC." (PMID 29207598, 2017). "Brain metastatic cells derived from breast and lung cancer secrete plasminogen activator (PA) inhibitory serpins, which protect against the loss of cell adhesion capacity caused by L1 cell adhesion molecule (L1CAM) degradation and against Fas-dependent apoptosis mediated by reactive astrocytes." (PMID 39408656, 2024). "Furthermore, PIK3C2G, FIBIN, CHRNA1, NPNT, MEOX1, and POU2F2 linked obesity and lung cancer, while PTPRQ, SSUH2, CILP2, CDH2, ABCA12, CPXM1, and L1CAM linked hypertension and lung cancer." (PMID 36685671, 2023). "Breast and lung cancers that metastasize to the brain were shown to utilize the cell adhesion molecule L1CAM for migration along capillaries." (PMID 40958870, 2025). "Recently, our team has demonstrated that brain metastases from lung cancer show an aberrant expression of the L1CAM and that the L1CAM is an independent predictive factor of poor prognosis for brain metastases from lung cancer." (PMID 36387224, 2022). "JMJD2C reduces the level of trimethylation on the histone H3 at lysine 9 (H3K9), and activate the genes lysyl oxidase-like protein 2 (LOXL2) and L1 cell adhesion molecule (L1CAM) that can promote lung cancer metastasis." (PMID 33109235, 2020). "Tischler found a subset of nonsmall cell lung cancer with vessel tropism and increased metastasis aberrantly expresses L1CAM, and it served as a novel poor prognostic marker." (PMID 32509846, 2020). "It has been shown that inhibition of HIF-1 leads to inhibition of L1CAM and subsequent blockage of tumor growth and metastasis in lung cancer." (PMID 29615539, 2018). "Recently, SerpinB2, Neuroserpin and L1CAM were reported to be key drivers in experimental studies of lung cancer dissemination, with special focus on the biology of brain metastases." (PMID 29207598, 2017). "In the present study, the L1CAM expression in the metastatic brain lesions or peripheral blood and biomarkers mapping the systemic immune-inflammation state was investigated in patients with brain metastases from lung cancer." (PMID 36387224, 2022). "In conclusion, the L1CAM expression in either metastatic brain lesion or peripheral blood is positively correlated with the peripheral platelet count in patients with brain metastases from lung cancer." (PMID 36387224, 2022). "Our study found that the L1CAM expression in either metastatic brain lesion or peripheral blood is positively correlated with the peripheral platelet count in patients with brain metastases from lung cancer." (PMID 36387224, 2022). "In the present study, 98 patients with brain metastases from lung cancer who received neurosurgical tumor resection in our institute were included in the final analysis to explore the relationship between the L1CAM expression in brain metastases and CBC biomarkers." (PMID 36387224, 2022). "In the present study, we firstly tested the L1CAM expression in the metastatic brain lesion in patients with brain metastases from lung cancer who were treated with neurosurgical tumor resection and the L1CAM expression in peripheral blood in the one treated with non-surgical antitumor management." (PMID 36387224, 2022). "The L1CAM expression in either the metastatic brain lesion or peripheral blood is positively correlated with the peripheral platelet count in patients with brain metastases from lung cancer." (PMID 36387224, 2022). "Additionally, involvement of L1CAM in spreading on the abluminal surface of capillaries has been demonstrated in a xenograft model of brain metastasis with human breast and lung cancer cells." (PMID 29432466, 2018).
lung carcinoma (continued). "While L1 cell adhesion molecule (L1CAM; CD171) was originally discovered in the nervous system due to its important function for axon guidance and cell migration, it has also been shown to be a crucial factor for tumour cell dissemination and metastasis in colorectal, breast, kidney and lung cancer." (PMID 32291413, 2020). "Collectively, these findings identify exosomal L1CAM as a key regulator of brain-specific metastasis and support the clinical utility of the L1CAM/ITGB3 panel as a noninvasive biomarker for BrM in lung cancer." (PMID 41675572, 2026). "In the present study, 40 patients with brain metastases from lung cancer who received non-surgical antitumor management in our institute were included to explore the relationship between the L1CAM expression in peripheral blood and CBC biomarkers." (PMID 36387224, 2022). "However, little is known about the relationship between the L1CAM expression and the systemic immune-inflammation macroenvironment beyond the TME in brain metastases from lung cancer." (PMID 36387224, 2022). "Cell line studies in human pancreatic ductal adenocarcinoma, endometrial, breast and lung cancer cells showed that treatment with TGF-β1 initiated transcription factor slug, not only resulting in upregulated L1CAM/vimentin and downregulated E-cadherin, but also in enhanced cell invasion." (PMID 29152102, 2017). "Several other identified TAAs for lung cancer, like the folate receptors α and β, tyrosine kinase receptor EphA2, phosphatidylinositol proteoglycan 3 GPC3, CD44v6, Lewis-Y antigen, IL-13Rα2, L1 cell adhesion molecule (L1CAM) and disialoganglioside GD2, are yet to be tested." (PMID 40922740, 2025). "Currently, no data on L1CAM are available for brain metastasis samples from lung cancer." (PMID 35525225, 2022).
glioblastoma (27 papers, 2011 to 2025). The most malignant astrocytic tumor (WHO grade IV). "L1CAM has been implicated in the stem cells of other tumor types such as glioblastoma and as a marker for pluripotent stem cells." (PMID 32374759, 2020). "Cell adhesion molecule L1 (L1CAM) is a cell surface glycoprotein that promotes tumor migration in proliferation in glioblastomas." (PMID 40430568, 2025). "Researchers found that inhibiting FGFR (using agents like PD173074), integrins, or FAK effectively reduced L1CAM-stimulated glioblastoma cell movement and growth." (PMID 41567627, 2025). "Subsequent studies revealed that L1CAM is elevated in different types of human cancers, including pancreatic neuroendocrine tumors, glioblastoma, and colorectal cancer." (PMID 33710805, 2021). "Inhibiting FGFR, integrin or FAK signaling depletes the L1CAM response in L1CAM-positive glioblastoma cells, suggesting an L1CAM-FGFR-integrin-FAK signaling axis is required for L1CAM driven motility and proliferation." (PMID 34068954, 2021). "L1CAM-related cancer stemness has also been reported in glioblastoma where L1CAM regulates the checkpoint-mediated DNA damage response of CSC by modulating the expression of the early checkpoint response component NSB1." (PMID 34645505, 2021). "In another study, Held-Feindt showed that TGF-β1 signaling regulated L1CAM expression in glioblastoma, and L1CAM conferred resistance to temozolomide." (PMID 32509846, 2020). "The authors found that several CSC markers were enriched in the glioblastoma stem cell population, and L1CAM was one of them." (PMID 32429448, 2020). "Through a loss-of-function approach, the authors showed that silencing L1CAM in glioblastoma stem cells (GSC), defined by CD133 expression, reduced their growth and survival both in vitro and in vivo." (PMID 32429448, 2020). "A transcriptomic analysis of LGR5-silenced glioblastoma stem cells showed that L1CAM is downregulated and therefore is regulated by LGR5, altough the molecular mechanism remains to be elucidated." (PMID 32429448, 2020). "Another level of regulation includes the control of caspases, as L1CAM suppresses transcription of caspase-8 in glioblastoma." (PMID 31455004, 2019). "The cell adhesion molecule L1CAM promotes glioblastoma cell motility and proliferation." (PMID 41567627, 2025). "Additionally, nuclear L1CAM signalling augments the DNA damage checkpoint response and radioresistance of glioblastoma stem cells." (PMID 34078883, 2021). "Glioblastoma provides also a prototypical example of L1CAM’s role in chemoresistance." (PMID 32429448, 2020). "In glioblastoma, nuclear translocation of L1CAM-CT is required for radioresistance." (PMID 31455004, 2019). "Similarly, in glioblastoma, L1CAM promotes self-renewal and confers temozolomide resistance by maintaining neural stem cell-like properties, whereas in endometrial cancer, it contributes to the formation of cancer initiating cells and resistance to paclitaxel by activating EMT-associated pathways." (PMID 40429728, 2025). "Cheng and colleagues provided supporting evidence for this phenomenon, showing that L1CAM was highly expressed in a population of glioblastoma stem cells in the invasive fronts of primary GBMs, and targeted L1CAM might reduce GBM cancer invasion and tumor recurrence." (PMID 32509846, 2020). "Interestingly, L1CAM was found aberrantly expressed both in the secretome and in the cell-associated proteome of GNS, suggesting that its function is specifically involved in the stem cell compartment of glioblastoma." (PMID 32429448, 2020). "Indeed, L1CAM has been frequently employed to identify stem-like population in glioblastoma." (PMID 32429448, 2020). "The L1CAM could stimulate glioblastoma cells motility and proliferation." (PMID 27349736, 2016).
glioblastoma (continued). "Anderson revealed that L1CAM acted through integrin, focal adhesion kinase (FAK), and fibroblast growth factor receptor (FGFR) signaling pathways in glioblastoma derived cell lines to increase their motility, proliferation, and invasiveness." (PMID 32509846, 2020). "They showed that L1CAM promoted chemoresistance to temozolomide, which was mediated by TGF-β1 and led to the down-regulation of caspase-8 in both stem-like and bulk glioblastoma cells." (PMID 32429448, 2020). "Furthermore, in glioblastoma multiforme (GBM) cancer cells, highly expressed L1CAM was previously found to increase DNA damage checkpoint activation by NBS1 upregulation via c-MYC 3 h after radiation, resulting in radioresistance." (PMID 34078883, 2021). "Markers for glioblastoma stem cells such as CD133, CD15, integrin-α6, L1CAM might be informative to identify these cells but cannot be conclusively linked to a stem cell phenotype." (PMID 22685459, 2012). "Specifically, all the L1CAM positive cases were diffuse gliomas, include 36 cases of WHO II (26 astrocytomas and 10 oligodendrogliomas), 28 cases of WHO III (18 anaplastic astrocytomas and 10 anaplastic oligodendrogliomas), and 45 cases of WHO IV (glioblastoma/GBM)." (PMID 32509846, 2020).